BDNF (brain derived neurotrophic factor)
Diseases named in the same sentence as BDNF in open-access papers (continued):
Sharing a sentence is not in itself a finding about the gene and the disease.
memory impairment (301 papers, 2007 to 2026). "Both Cistanche deserticola polysaccharide and total glycosides upregulate the expression of synapsin, growth-associated protein 43 (GAP43), PSD-95, and BDNF, enhancing synaptic plasticity in the hippocampal region and improving learning and memory impairments." (PMID 40584613, 2025). "Clinical studies have shown that memory impairments in patients are associated with the BDNF Val66Met polymorphism, a condition where a methionine (Met) is substituted for valine (Val) at residue 66 of the BDNF protein, leading to reduced BDNF availability." (PMID 40715999, 2025). "This evidence further strengthens the suggestion that cognitive dysfunction is influenced by the BDNF rs6265 polymorphism, as our findings showed that carrying the BDNF rs6265 Met/Met genotype was linked with learning and short‐term memory impairment." (PMID 38379321, 2024). "Many studies on the beneficial effects of foods on memory impairment using animal models, such as AD models, have evaluated their association with BDNF signaling pathway activation, that is, BDNF protein expression, pTrkB/TrkB ratio, and pCREB/CREB ratio." (PMID 38257270, 2024). "The epileptic state is associated with memory impairment in this test in rats, but BDNF administration correlated with a more intense study of the novel object by rats after epilepsy." (PMID 39408863, 2024). "Roxadustat improves memory impairment by reversing the decline in memory-associated cAMP response element-binding protein (CREB)/brain-derived neurotrophic factor (BDNF) signals in the hippocampus." (PMID 36724056, 2023). "Fermented Codonopsis lanceolate reduced memory impairment caused by scopolamine, inhibited AChE activity and increased BDNF level and CREB phosphorylation in hippocampal tissue." (PMID 35624749, 2022). "On the other hand, BDNF supplementation indeed did successfully alleviate tauopathy-induced memory impairments by inhibiting neuron loss, synaptic degeneration, and impaired neurogenesis." (PMID 35090576, 2022). "Increased levels of pro-BDNF at the hippocampal level are associated with memory loss and intra-hippocampal administration of anti-proBDNF antibodies reduces cognitive dysfunction." (PMID 35911894, 2022). "In particular, neuronal cell damage in the fear circuit region causes memory impairment through a decrease in brain-derived neurotrophic factor (BDNF), increases in proinflammatory cytokines, and changes in synaptic plasticity." (PMID 35251208, 2022). "On the other hand, downregulation of BDNF expression caused cognitive and memory impairment in BDNF-knockout mice." (PMID 36076858, 2022). "In our study, the STZ-ICV-induced disruption of adult neurogenesis and loss in BDNF-related neuroprotection was accompanied by spatial learning and memory impairment assessed in the MWM test." (PMID 36555093, 2022). "In male rats, long‐term restraint stress increased memory impairments as assayed in the PA test, which was an effect associated with decreases in hippocampal BDNF gene expression." (PMID 33811472, 2021). "The increased p75NTR and pro-BDNF expression are associated with a variety of pathological processes such as memory impairment, increased susceptibility to epileptic seizures and neuronal apoptosis." (PMID 34604212, 2021). "LPS causes systemic neuroinflammation, resulting in memory impairment by the modulation of NF-κB-mediated BDNF/CREB expression." (PMID 32158447, 2020). "Logistic regression analysis revealed that older age, less physical activity, hippocampal atrophy, and lower BDNF levels were independently associated with memory impairment determined by the Rivermead Behavioral Memory Test." (PMID 33020545, 2020). "Previous studies have shown that SPS induced memory impairments are associated with substantial reductions in the expression level of BDNF mRNA in the hippocampus, resulting in poor performance on hippocampus dependent tasks." (PMID 30621666, 2019).
memory impairment (continued). "Although decreased levels of these factors have been associated with age-related hippocampal dysfunction and memory impairment, increased BDNF levels resulting from aerobic exercise appears to ameliorate hippocampal deterioration and improve memory function." (PMID 30832372, 2019). "We used the Wechsler Memory Scale-third edition (WMS-III), the presence of the BDNF Val66Met polymorphism, and plasma concentrations of BDNF to investigate the association between memory impairment and BDNF in BD-II disorder." (PMID 30542371, 2018). "A single nucleotide polymorphism (SNP) in the BDNF gene (Val66Met) has been shown to influence the activity of the BDNF protein and cause subsequent memory impairment and harm avoidance." (PMID 26733829, 2015). "Gil-Bea and colleagues have shown that cholinergic deafferentation of the hippocampus induces memory impairments in the water maze test that are correlated with hippocampal activity-regulated cytoskeleton associated protein (Arc) and BDNF downregulation." (PMID 25849905, 2015). "The Met allele of the BDNF Val66Met polymorphism has been linked with reduced BDNF activity, memory impairment and harm avoidance." (PMID 24433458, 2014). "In this study, memory impairment was associated with down-regulated BDNF and TrK B and up-regulated TrK A and p75, and greater expression of p75 receptors in cholinergic neurons is believed to be responsible for cholinergic neuronal apoptosis and degeneration." (PMID 23651534, 2013). "In addition, diets high in fat, and sugar can reduce BDNF expression, which is associated with memory impairment." (PMID 36839199, 2023). "Our previous study showed that MSD significantly downregulated brain-derived neurotrophic factor (BDNF) expression and upregulated synaptotagmin-1 (Syt-1) expression in the hippocampus, which was associated with spatial learning and memory impairment detected in the MWM." (PMID 37168717, 2023). "BDNF is a molecule that is abundantly present in the hippocampus and it has been shown that the amount of this substance is reduced in diabetes and can be effective in the process of memory impairment caused by diabetes." (PMID 37970441, 2023). "The BDNF Val66Met SNP reduces the expression and the activity‐dependent release of BDNF and has been correlated in humans with a smaller hippocampal volume, memory impairments, increased predisposition to develop neuropsychiatric and neurodegenerative disorders, and altered vulnerability to stress." (PMID 35908196, 2022). "However, a reduction in BDNF mRNA expression is associated with memory impairment in dopamine transporter-knockout mice." (PMID 36552126, 2022). "Both estrogen and BDNF have been shown to exert highly potent effects in the hippocampus, and thus have been explored as potential pathological mediatory and therapeutic targets in psychiatric conditions characterized by memory loss." (PMID 35090576, 2022). "However, learning and memory impairment cases are detected in HIV-positive patients that can be associated with a decrease in BDNF levels." (PMID 35628626, 2022). "An adiponectin-based therapeutic which can enhance hippocampal BDNF levels could serve as a pharmacological intervention for restoring diabetes-associated learning and memory impairment." (PMID 34164760, 2021). "Numerous studies have suggested that BDNF and its receptor TrkB signaling alterations were also implicated in synaptic plasticity and memory impairments, and evidence suggested that this might be related to STEP dysregulation." (PMID 34195199, 2021). "Next, we tested whether reduced BDNF levels cause memory impairments that could also affect performance in motor tasks." (PMID 32651187, 2020). "Taken together, these results supported our hypothesis that enhanced basal forebrain BDNF/TrkB signaling acted as a compensation to counteract fear memory impairments caused by sleep deprivation." (PMID 32157827, 2020).
memory impairment (continued). "In conclusion, our study demonstrated that chronic ketamine (25 mg/kg) administration causes spatial learning and memory impairment in SD rats, and that this deficit might be associated with decreased serum BDNF levels." (PMID 33088278, 2020). "Furthermore, previous treatment with benzodiazepines did not predict BDNF, and in some cases, benzodiazepines are associated with memory impairment and reduction of BDNF expression in the hippocampus; thus, further studies should analyze this topic." (PMID 32410966, 2020). "Due to the role of BDNF in neural plasticity, there could be a link between BDNF expression and the cognitive symptoms associated with memory impairments." (PMID 31440144, 2019). "Indeed, neurons in the hippocampus of aged animals respond to Aβ-induced toxicity by showing atrophy and a down-regulation of BDNF and pCREB expression that are associated with learning and memory impairment." (PMID 26980711, 2016). "The reduced BDNF concentration and neuronal loss in the mPFC and hippocampus may have manifested their effects as memory impairment." (PMID 27119005, 2016). "Moreover, previous studies showed the crucial role of tropomyosin receptor kinase B (TrKB) associated brain-derived neurotrophic factor (BDNF) signaling in protection against memory impairment and regulation of neurogenesis in the hippocampus of AD." (PMID 28053983, 2016). "Moreover, the Met allele of the BDNF Val66Met polymorphism has been found associated with a reduced BDNF activity, memory impairment, harm avoidance, brain volume reduction, and has been also shown to affect intracellular trafficking." (PMID 26005424, 2015). "Downregulation of BDNF expression is associated with memory impairment." (PMID 25031604, 2014). "A single-nucleotide polymorphism in the human BDNF gene, resulting in a valine to methionine substitution (Val66Met) in the prodomain, has been shown to lead to reduced activity-induced BDNF secretion and memory impairment." (PMID 17629449, 2007). "In addition, the chronic phase was also characterized by changes in neuronal molecular markers indicative of axonal and synaptic damage (alterations in neurofilaments and PSD-95) and impaired neurotrophism (decreased BDNF levels), which were associated with memory impairment." (PMID 39266325, 2024). "Therefore, we investigated whether the protective effects of GEGR on SP-induced memory impairment is linked to the regulation of BDNF secretion and the receptor signaling pathway." (PMID 31623364, 2019). "In addition, such memory impairment is correlated with various BDNF polymorphisms." (PMID 30542371, 2018). "Thus, we decided to assess whether the effect of steamed and fermented C. lanceolata ameliorated memory impairment was linked to the increased BDNF and CREB activation in the hippocampus of mice." (PMID 25031604, 2014). "We assessed the long-term therapeutic effects of BDNF elevation in the hippocampus on learning and memory impairments." (PMID 41480410, 2026). "The possible therapeutic effect of short‐ and long‐term QET on the 72 SD‐induced recognition memory impairment and hippo BDNF level was evaluated." (PMID 39829139, 2025). "offered protection to mice against memory impairment induced by scopolamine, enhancing BDNF expression and reducing acetylcholinesterase activity in the hippocampus." (PMID 41415845, 2025). "Reduced hippocampal neurogenesis and dysregulated neurotrophic signaling, including BDNF/TrkB and PI3K–AKT–CREB pathways, have been linked to memory impairment and increased vulnerability of neuronal circuits in AD and related conditions." (PMID 41515125, 2025). "Perturbed BDNF and CREB within the hippocampus have been previously associated with memory loss and cognitive dysfunction." (PMID 41354896, 2025).
memory impairment (continued). "This is important because decreased BDNF levels are associated with mental illness in patients, whereas, overexpression of BDNF leads to abnormal activation of neuronal circuits, resulting in learning and memory impairments." (PMID 39726067, 2024). "Notoriously, AngIV has a neuroprotective effect against memory impairment in diabetic rats by increasing the expression of neuronal BDNF." (PMID 37953501, 2024). "Even in case of advanced memory impairment, cardiovascular exercise has been found to elevate BDNF levels, which in turn enhance hippocampal neuroplasticity and memory function in mice across various age groups from young to old." (PMID 39286235, 2024). "As well, numerous experimental studies showed that activation of the Ang1‐7/MASR axis promotes expression of the BDNF/TrkB axis, thereby reducing cognitive dysfunction and memory impairment." (PMID 37953501, 2024). "Treatment with deferiprone (an oral iron chelator) rescued the expression of NQO1, restored memory, and increased hippocampal brain-derived neurotrophic factor (BDNF) levels in an experimental animal model of memory impairment." (PMID 38167027, 2024). "In previous studies, we found that RGLS prevented the formation of learning and memory impairments in the same rat model of sAD by decreasing Aβ expression and Tau hyperphosphorylation and modulating BDNF-TrkB signaling in the hippocampus." (PMID 38720773, 2024). "Administration of a small non‐antihypertensive dose of AT1 receptor blocker candesartan (0.1 mg/kg) in mice for 15 days inhibits LPS‐induced memory impairment by increasing expression of the BDNF/TrkB axis, which inhibits TLR4 and NF‐κB." (PMID 37953501, 2024). "This evidence was further confirmed in mice injected with Aβ42O, in which oral treatment with fingolimod restored the physiological levels of BDNF and, as a consequence, ameliorated memory impairment." (PMID 35851748, 2023). "MetS rats with GCJ treatment improved memory impairment, enhanced neuron density, and increased the expressions of eNOS, BDNF, and pERK/ERK but suppressed AChE in both areas." (PMID 37564141, 2023). "Signally reduced mRNA levels of PSD-95 and BDNF were found in ApoE-/- mice, which were markedly increased by Atorvastatin, further verifying the protective property of Atorvastatin against the memory impairment in hypercholesterolemia mice." (PMID 38048213, 2023). "In summary, we observed that this dietary supplement restored D-gal-induced spatial and memory impairment, accompanied by the up-regulation of BDNF, and the enhancement of antioxidant and anti-neuroinflammatory abilities." (PMID 35866081, 2022). "Modulation of BDNF and its downstream receptor, Trkβ, is suggestive of the neuroprotective potential of TCP supplementation against age-associated synaptic loss and memory impairments." (PMID 35966795, 2022). "Our results showed that the STZ-ICV evoked spatial learning and memory impairment and disturbances in adult neurogenesis and BDNF expression in both examined brain structures." (PMID 36555093, 2022). "Carvacrol inhibits memory impairment and inflammation in LPS-treated rats, the carvacrol showed anti-inflammatory effects mediated by BDNF and TLR4 regulation." (PMID 36557252, 2022). "A single nucleotide polymorphism rs6265 in BDNF gene, known as Val66Met, impacts intracellular trafficking and activity-dependent secretion of BDNF, which can subsequently lead to memory impairment." (PMID 35815020, 2022). "Accordingly, the intrahippocampal injection of BDNF improved the memory function of animals in MWM tests, while the administration of anti-BDNF antibodies led to memory impairment." (PMID 36552126, 2022). "CREB inhibitor administration suppressed the resveratrol-rescued abnormal hippocampal ultrastructural changes and aggravated spatial learning and memory impairment by inhibiting CREB/BDNF pathway activation in the hippocampus." (PMID 36478990, 2022).
memory impairment (continued). "Soy-B has been shown to attenuate LPS-induced memory impairment in mice via NF-κB-mediated BDNF expression and prevent scopolamine-induced memory impairment." (PMID 35626478, 2022). "Amelioration Aβ-induced memory impairment; high recovery of vessel density in the hippocampus; upregulation of BDNF; significant decrease in oxidative stress; synaptic enhancement." (PMID 34179015, 2021). "A surgery-induced decrease in SCFA expression coupled with exacerbated spatial learning and memory impairment reduced BDNF levels and amplified neuroinflammatory responses." (PMID 34168535, 2021). "Infection with BVDV considerably decreases the expression of BDNF, CREB, and SCF, causing memory impairment due to the reduced synaptic plasticity in the hippocampus." (PMID 34579276, 2021). "The other mechanism that is likely to play a role in memory impairment during COVID-19 is the decrease of ACE2-mediated brain-derived neurotrophic factor (BDNF) activity." (PMID 34640355, 2021). "In the same way, Angiotensin II type 1 receptor (AT1) blockade prevented memory impairment via up-regulation of BDNF." (PMID 34957187, 2021). "Lactobacillus mucosae NK41 suppresses Escherichia coli-induced memory impairment with the attenuation of gut dysbiosis, suppression of hippocampal NF-κB activation, and induction of hippocampal brain-derived neurotrophic factor (BDNF) expression in mice." (PMID 34579150, 2021). "Phlorotannin-rich extract from Ishige foliacea improved the cognitive function by upregulating the ERK/CREB/BDNF signaling pathway and preventing the AChE activity and oxidative stress on the scopolamine-induced learning and memory impairment mouse model." (PMID 33673531, 2021). "The treatments with an anti-BDNF antibody or BDNF antisense mRNA induce memory impairments related to a reduction of LTP and ERK signaling." (PMID 33911138, 2021). "Taken together, the present results show that the nacre polysaccharide recovers scopolamine-induced memory impairment by increasing the expression of BDNF and NGF and showing antioxidant and anti-inflammatory activities." (PMID 33804892, 2021). "Intranasal administration of antagomir miR-206 attained to the brain and enhanced BDNF levels and improved memory impairment in AD animal model." (PMID 32944919, 2021). "Phlorotannin-rich extract from brown alga Ishige foliacea attenuated scopolamine-induced memory impairment with the regulation of cyclic AMP-response element-binding protein (CREB)-brain-derived neurotrophic factor (BDNF) expression." (PMID 34436273, 2021). "Z-guggulsterone (Z-GS), an inhibitor of FXR, can improve the scopolamine-induced memory impairment through enhancement of the signalling of brain-derived neurotrophic factor (BDNF)." (PMID 32450881, 2020). "BDNF-signaling is impaired by ELS; early traumas can evoke significant memory impairments in adulthood in association with reduced BDNF levels." (PMID 32719625, 2020). "Another study has investigated the use of a pharmacological approach indented to promote BDNF in Ts65Dn mice, a mouse model of DS, and provide evidence that the BDNF-mimetic drug 7,8-dihydroxyflavone rescued learning and memory impairments." (PMID 32092951, 2020). "Centella asiatica ameliorates memory impairment and induces expression of hippocampal brain-derived neurotropic factor (BDNF) in chronically stressed rats." (PMID 30956976, 2019). "Anaesthesia and surgery-induced H3K9 trimethylation and the long-term transcriptional repression of BDNF, resulting in long-term (more than 24 h) memory impairment." (PMID 31708739, 2019). "Repetitive electrical foot shock was chosen for this study because this model was previously used in the report on C. asiatica effect in preventing memory impairment and the reduction of BDNF concentration upon chronic stress in rats." (PMID 30956976, 2019).